IL6 (interleukin 6)
Diseases named in the same sentence as IL6 in open-access papers (continued):
Sharing a sentence is not in itself a finding about the gene and the disease.
pneumonia (continued). "We found that IL-6 was the independent predictor of the severity of lung injury in COVID patients with pneumonia after controlling for confounders." (PMID 32727465, 2020). "Ticagrelor administration to patients within 48h of pneumonia diagnosis demonstrated anti-inflammatory effect with reduced PLAs in circulation, lowered IL-6 levels and improved lung function with a decrease in supplemental oxygen requirements." (PMID 32092903, 2020). "In our patients, median and highest levels IL-6 levels on admission were 10 pg/mL and 49 pg/mL in mild disease/pneumonia group and 43 pg/mL and 168 pg/mL in SARI/critical disease group." (PMID 32682358, 2020). "The secretion of proinflammatory cytokines such as interleukin (IL)-8 and IL-6 by respiratory epithelial cells, which is induced by infection of respiratory bacteria such as Streptococcus pneumoniae, contributes to the onset of pneumonia." (PMID 33114582, 2020). "YD was verified to treat LPS-induced pneumonia by regulating the inflammatory factor IL-6, which was a predicted target." (PMID 32493296, 2020). "The NIHSS score, white blood cell (WBC) count, rate of pneumonia, and plasma level of IL-6 increased across the tertiles of the GC sensitivity index whereas the TNFα release ex vivo decreased." (PMID 32107751, 2020). "It has been proven in a study of pneumococcal infection following influenza that concomitant neutralization of IFN-r and IL-6 significantly reduced the severity of pneumonia and bacteremia." (PMID 32486412, 2020). "Particularly, since pneumonia and ARDS are associated with a cytokine storm, drugs belonging to therapeutic classes as anti-IL-6, anti-TNF, and JAK inhibitors are currently studied." (PMID 32527304, 2020). "Still, the recently published double-blinded randomized XANTHIPPE study comparing ticagrelor to placebo in pneumonia, demonstrated a significant reduction in plasma IL-6 levels in the ticagrelor group." (PMID 32092903, 2020). "The use of immunosuppressants, specifically the IL-6 inhibitors, in the management of SARS-CoV-2-associated pneumonia is an attractive option to overcome the inflammation and CRS in the lungs." (PMID 33292350, 2020). "Both Serum IL-10 (p = 0.002) and IL-6 levels (p = 0.03) were also significantly higher in those who deceased or developed severe pneumonia, than in those with mild illness during early illness." (PMID 33199778, 2020). "IL-6–mediated enhancement of the antibacterial responses presents a unique direction for research in combating complicated influenza pneumonia and secondary bacterial infections." (PMID 32038632, 2019). "IL-6 levels rose by 2 hour and persisted at 18 hours in both models in the blood; in the pneumonia model, IL-6 levels in the lung rose in a delayed fashion, so that they significantly elevated by 18 hours, but not at 2 hours in most mice." (PMID 31318907, 2019). "The BS3 adjusted cytokines IL-6 and IP-10 were associated with shock, while IL-8 and MCP-1 were associated with both shock and pneumonia-ARDS." (PMID 31275311, 2019). "To validate our findings, we measured IL-6 levels in the serum of patients with different pneumonia and healthy controls." (PMID 32038632, 2019). "Concomitant neutralization of IFN-γ and IL-6 significantly reduced the degree of pneumonia as well as bacteremia compared to the control group, indicating a positive effect for the host during secondary bacterial infection." (PMID 31474978, 2019). "The data indicated significant differences in the cytokine levels depending on the aetiology of pneumonia: decreased IL-6 for atypical bacteria, increased IL-10 for viral, increased IL-8 for Enterobacter spp., and increased TNF-α for L. pneumophila." (PMID 31183362, 2019). "Here we show that the clinically relevant co-infected mice displayed dramatically elevated IL-6 levels; which was also observed in patients with co-infected pneumonia." (PMID 32038632, 2019).
pneumonia (continued). "The BS3 cytokines IL-6 and IP-10 had an association with shock, while IL-8 and MCP-1 had an association with both shock and pneumonia-ARDS." (PMID 31275311, 2019). "These patients did not exhibit the rise in 5,6-DHET and 8,9-DHET or the fall in IL-6, that was seen with recovery from pneumonia or uncomplicated brain injury." (PMID 30283005, 2018). "A recent human study demonstrated that serum IL-6 and TNF levels are associated with early mortality of patients with pneumonia." (PMID 29922273, 2018). "Among the survivors, IL-6 levels > 83.15 pg/mL on day 1 predicted subsequent major complications, such as pneumonia." (PMID 29758073, 2018). "IL-6 is usually highly expressed when cells are stimulated by bacterial LPS, viruses and cytokines such as IL-1, IFN and TNFα, and the concentration of IL-6 and TNFα can reflect the severity of pneumonia." (PMID 28899359, 2017). "IL-6 levels were sensitive to the development of infections and showed an increase in patients who developed pneumoniae." (PMID 29194369, 2017). "Severe pneumonia patients have shown increased serum levels of IL-6, IL-8 and IL-10, and the excess of IL-6 and IL-10 are associated with an increase in mortality from 4.8% to 11.4%." (PMID 28617807, 2017). "The increase of CINC-3 after 20 h of pneumonia and increased levels of TNF-α and IL-6 after 40 h of pneumonia probably reflects the inflammatory reactions during the S. pneumoniae pneumonia." (PMID 27683129, 2016). "The decrease in the IL-6:IL-10 ratio to 3 in patients with severe pneumonia on D8 coincided with the temperature and respiratory frequency recovery to normal levels." (PMID 27905908, 2016). "Regarding the cytokine levels, the reduction of IL-6 serum levels during recovery of children with severe pneumonia was the effect more pronuanced." (PMID 27905908, 2016). "The ROC curve of the IL-6:IL-10 serum levels ratio discriminated severe pneumonia cases at admission, and persistence of infection in the third day of antibiotic therapy, with positive predictive values of 93% and 89%, respectively." (PMID 27905908, 2016). "The pathophysiology of some patients with a fatal outcome from influenza pneumonia is characterized by elevated levels of proinflammatory cytokines such as IL‐6, tumor necrosis factor‐α, and IFN‐γ, sometimes referred to as the cytokine storm." (PMID 26976612, 2016). "The balance between IL-6 and IL-10 serum levels showed to be a more discriminative marker for severity definition and evaluation of recovery in patients with pneumonia." (PMID 27905908, 2016). "Previous studies have reported a correlation between IL-1β and IL-6 overexpression and some clinical, radiological and immunological findings, such as pneumonia and ARDS, in both children with seasonal influenza and murine models." (PMID 26657940, 2015). "In patients with unilateral pneumonia, Dehoux and colleagues found that the IL-6 level in bronchoalveolar lavage fluid obtained from the infected lung was significantly higher than that in the uninfected side or in the plasma." (PMID 25708204, 2015). "Since TCZ inhibits IL-6's actions, it is possible that these early symptoms of pneumonia were masked by the TCZ treatment." (PMID 24872899, 2014). "The concentrations of the cytokines interleukin (IL)-1β, IL-6, keratinocyte-derived cytokine (KC) and IL-10 in lung homogenate were increased by pneumonia and, to a lesser extent, by MV." (PMID 24731244, 2014). "In pneumonia, MV led to a further dramatic increase of IL-1β, IL-6 and KC, while IL-10 levels remained unaffected." (PMID 24731244, 2014). "Previous studies, in fact, reported the correlation between IL-1β and IL-6 up-regulation and some clinical and radiological findings, such as pneumonia and ARDS, both in experimental animal models and in children with naturally acquired seasonal influenza A." (PMID 23737648, 2013). "The current study shows that the risk factors for pneumonia are age, NIHSS, dysphagia, IL-6 and CRP." (PMID 23935729, 2013).
pneumonia (continued). "Similar findings concerning elevated IP-10 and IL-6 levels in cases of pediatric pneumonia were reported from Korea." (PMID 23468921, 2013). "In patients with a severe course of pneumonia, we found significantly increased IL-6 and LBP concentrations." (PMID 22348735, 2012). "We previously showed that Pigeon04 highly induced the expressions of pro-inflammatory cytokines such as IL6 and TNFα in the lungs of the infected mice, resulting in severe pneumonia." (PMID 21826229, 2011). "EGR1 and IL-6 mRNA expression correlated with anastomotic leak and pneumonia at POD 3 by regression analysis (p = 0.021)." (PMID 20969744, 2010). "• At the time of HAP diagnosis, TNF-α, IL-1β, IL-6, IL-8, IL-10 and E-selectin were significantly increased in pneumonia patients with subsequent septic shock compared to patients without subsequent septic shock." (PMID 16280065, 2005). "In the pneumonia group with subsequent septic shock, levels of IL-1β, IL-6, IL-8 and IL-10 were significantly increased before the onset of septic shock compared to patients without subsequent septic shock." (PMID 16280065, 2005). "For instance, future studies could test whether inhibiting IL-6 signaling may reduce inflammatory damage and improve clinical outcomes in patients with severe pneumonia." (PMID 41597746, 2026). "IL-6 is an important cytokine that is often significantly elevated in patients with pneumonia." (PMID 41293058, 2025). "In addition, hyperoxia can cause an inflammatory response along with a release of pro-inflammatory cytokines, such as interleukin 6 (IL-6), and an activation of immune cells, triggering neuroinflammation and pulmonary diseases such as pneumonia." (PMID 39856357, 2025). "Similarly, clinical data indicate that the Th17/Treg ratio and IL-6 levels were higher in the RSVP group compared to groups with common pneumonia and healthy controls." (PMID 41425878, 2025). "In summary, children with severe pneumonia are at risk of developing ACD, which may be influenced by factors such as mechanical ventilation, CRP, PCT, IL-6, and IgA levels." (PMID 41234411, 2025). "Similarly, IL-6 levels were found to have a positive correlation with the severity of pneumonia in IAV-infected patients." (PMID 40565228, 2025). "Pneumonia is also an immune-mediated disease, with a median increase in Th1-associated cytokines and chemokines observed in patient serum samples, including IFN‐γ and IL-6, -7, and -8." (PMID 40041495, 2025). "Besides, another study also explored the immune reactions in Chlamydia psittaci pneumonia and they found psittacosis cases with pneumonia had higher levels of serum cytokines (G-CSF, IL-2, IL-6, IL-10, IL-18, IP-10, MCP-3, and TNF-α) than bronchitis cases." (PMID 40236451, 2025). "Interleukin (IL)-6, a representative pro-inflammatory cytokine, can directly induce SM atrophy in healthy rat models, suggesting that pneumonia accompanied by severe inflammation may influence muscle wasting." (PMID 40807081, 2025). "Children with severe pneumonia are at risk of developing ACD, which may be influenced by mechanical ventilation, CRP, PCT, IL-6, and IgA levels." (PMID 41234411, 2025). "Therefore, monitoring the levels of HBP and IL-6 in patients with pneumonia is of considerable clinical significance for assessing the severity of pneumonia and formulating reasonable treatment plans." (PMID 41293058, 2025). "Based on the results of this study, it is recommended to apply HBP and IL-6 in clinical practice according to the following scenarios to maximize their assessment value: for patients with severe pneumonia admitted to the emergency department or hospital, HBP should be tested first." (PMID 41293058, 2025). "Serum IL-6 levels were significantly elevated in children with pneumonia (median: 47.37 ng/L, IQR: 32.63–61.63) compared to controls (median: 13.14 ng/L, IQR: 9.69–17.19; p < 0.001), with a threshold of >18.06 ng/L achieving 96% sensitivity and 100% specificity." (PMID 41018059, 2025).
pneumonia (continued). "Relative to controls, cytokines that were significantly elevated in the pneumonia cohort at 24 and/or 48 h after inoculation (evolution phase) were IL‐1β, IL‐6, IL‐15, IL‐16, IL‐17a, IP‐10, MCP‐1, MIP‐1β, and TARC; IL‐5 was significantly elevated at 168 h (resolution phase)." (PMID 40947770, 2025). "This suggests that PLT and CRP expression may influence the occurrence of ACD, with CRP, PCT, and IL-6 being particularly significant factors contributing to ACD in children with severe pneumonia." (PMID 41234411, 2025). "Notably, IL-6 values were consistently increased in patients accompanied by pneumonia or requiring advanced respiratory support, underscoring its importance as a key indicator of inflammation and clinical burden." (PMID 41585373, 2025). "In our opinion, this is the first study to identify SNPs in antioxidant (SOD1, CAT, GPX1, NOS, HMOX1, and NQO1) and immunological (IL-1α, IL1B, IL6, TNF-α, IL10, LFA-1, CR2, IL17, IL13, DEFB123, SCART1, and ICAM1) genes as potential suspects for pneumonia resistance/susceptibility in Barki ewes." (PMID 40221769, 2025). "Retrospective cytokine analysis (pre-pandemic 2018–2019 vs. post-pandemic 2023–2024) revealed post-pandemic suppression of IL-6 (6.12 vs.3.82 pg/mL) and IL-8 (37.98 vs. 18.35 pg/mL), with resurgence in 2024, particularly in pediatric and pneumonia cases (P<0.05)." (PMID 41561089, 2025). "IL-6 and IL-8 are essential mediators in influenza pneumonia." (PMID 40572766, 2025). "CRP showed a significant increase in patients with post-COVID-19 pneumonia (9.57 ± 9.02 mg/L vs. 4.85 ± 2.80 mg/L, p = 0.046) as well as interleukin-6 (IL-6) levels that were substantially elevated in the pneumonia group (6.75 ± 6.59 pg/mL vs. 1.43 ± 1.77 pg/mL, p < 0.001)." (PMID 39202577, 2024). "This was probably attributable to greater expression of the genes associated with CC genotypes and their pro-inflammatory implications, supporting an earlier meta-analysis research linking them with global death rates, pneumonia, and immunobiological treatment procedures using IL-6 pathways." (PMID 39452786, 2024). "In the next steps, IL-15, IL-6, pneumonia, and IL-12 were rejected." (PMID 39335569, 2024). "In our study, patients with HIV and pneumonia exhibit immune dysregulation, characterized by elevated levels of proinflammatory cytokines (IL-6, IL-8, IL-18), anti-inflammatory cytokines (IL-1RA, IL-10), and chemokines (IP10, MCP-1, MIP-1β) in their plasma, compared to the HIV group." (PMID 38251391, 2024). "Similarly, systemic IL-6 and Il-10 were upregulated at the diagnosis of pneumonia and showed downward trends throughout treatment, but without showing significant differences among study groups." (PMID 36788582, 2023). "Additionally, a recent study demonstrated that pulmonary administration of water-soluble curcumin reduced the production of proinflammatory cytokines, such as IL-6, in the serum of mice with Klebsiella-induced pneumonia." (PMID 37049389, 2023). "Elevated levels of IL‐6 and IL‐10 are indicative of the severity of inflammation and pneumonia." (PMID 37249293, 2023). "The Diagnosis and Treatment Protocol for Novel Coronavirus Pneumonia (Trial Version 7), issued by the National Health and Medical Commission of China, pointed out that clinical early warning indicators include elevated levels of IL-6." (PMID 38813035, 2023). "Several studies have reported that biomarkers of inflammation (such as leukocyte count and its subtypes, NLR, C-reactive protein, procalcitonin, and interleukin-6) predicted SAP events in IS patients, and there was a strong association between NLR and pneumonia severity." (PMID 37537542, 2023). "Accumulating evidence has confirmed that M. pneumoniae-induced pneumonia is closely associated with an elevated production of proinflammatory cytokines, including tumor necrosis factor-α (TNF-α) and interleukin- (IL-) 1β and IL-6." (PMID 37894556, 2023).
pneumonia (continued). "The higher levels of IL-6 and CRP observed in patients with pneumonia compared with the other group may be associated with the release of inflammatory mediators from type 2 pneumocytes as the virus enters cells via the ACE2 receptor and undergoes replication." (PMID 37631910, 2023). "In our study, IL-6 showed a trend of gradual upregulation with pneumonia severity, it was a selected feature for discrimination between uCAP and sCAP and correlated with the plasma levels of IL-8, which has been described to be significantly higher in sCAP patients compared to milder CAP." (PMID 37342494, 2023). "Meanwhile, we demonstrated that sequential serum IL-6 concentrations measurement in elderly patients with pneumonia is more important than simply determining whether the serum IL-6 concentration is above a certain threshold value at a single time point." (PMID 37214473, 2023). "In pneumonia, platelet activation may be upstream and contribute to inflammation since ticagrelor reduces IL-6 levels and mortality in this setting." (PMID 37520136, 2023). "A significant increase in IL-6 was detected in the sera of hamsters co-infected with SARS-CoV-2 and IAV, suggesting that IL-6 may be involved in the increased severity of pneumonia." (PMID 36677472, 2023). "We found that IL-6 was highly correlated to G-CSF in patients with pneumonia (R = 0.613)." (PMID 35382755, 2022). "Furthermore, in an LPS-induced acute lung damage model, blocking TRPV4 function prevented pneumonia and decreased the generation of proinflammatory markers, including IL-6, TNF-α, and ROS." (PMID 36552524, 2022). "There is a common molecular mechanism (IL-6) between pneumonia and sarcopenia." (PMID 36311511, 2022). "The levels of CXCL10 and IL-6 were significantly higher in patients with pneumonia and hypoxemia." (PMID 35237279, 2022). "Research indicates that the cytokine storms in severe pneumonia may be involved in high levels of interleukin (IL)-6 and monocyte chemoattractant protein-1/C-C motif chemokine ligand 2 (MCP-1/CCL2)." (PMID 36135185, 2022). "However, there are insufficient studies to support the value of IL-6 for the diagnosis of pneumonia in the first few days after cardiac surgery in adults." (PMID 35794529, 2022). "Acute pneumonia also increased the levels of IL-6, LPS and IFN-γ in the serum of mice." (PMID 35782123, 2022). "This cis-acting model provided more evidence that CRP signalling through the protein itself is odds increasing for pneumonia, even though more complex relationships likely exist with factors like IL-6 signalling: OR per SD CRP = 1.16 [95% CI: 1.09, 1.23], P = 7.23 × 10−5." (PMID 35768473, 2022). "The expression of GM-CSF and IL-6 was markedly upregulated in mice suffering from acute pneumonia, suggesting that LPS could stimulate lung inflammation and injury (p < 0.01)." (PMID 36373992, 2022). "A decrease of sIL-6Rβ may lead to the dysfunction of IL-6 with a potential contribution to the development of pneumonia." (PMID 36618370, 2022). "It has been elaborated that infections such as pneumonia are associated with high levels of interleukin-6 in thermally burn patients, regardless of the type of diet, while there were inconsistent elevations of tumor necrosis factors." (PMID 35889830, 2022). "Finally, when comparing cytokine levels among the patients with HMPV pneumonia, IL-6 and TNF-α levels were found to be significantly higher in the severe group than the mild group (p = 0.027 and 0.049)." (PMID 36496397, 2022). "Thus, IL-6 and G-CSF can be used as an excellent combination of biomarkers to predict the prognosis of influenza-related pneumonia." (PMID 35382755, 2022). "More importantly, we first reported that during the acute and early infection phases, AC larvae could induce mouse fatal pneumonia, with significant activation of Stat3/IL-6 signaling and enrichment of myeloid cells." (PMID 35617354, 2022).